ENSG00000285053 (novel protein, GGPS1-TBCE readthrough)
Gene: Protein-coding gene on chromosome 1 (235,328,570 to 235,448,952, forward strand). Ensembl gene ENSG00000285053.
Genetic constraint (gnomAD): Loss-of-function variants: 52 observed, 75.46 expected, observed/expected ratio (o/e) 0.69, 90% interval 0.55 to 0.87. The upper end of that interval is the gene's LOEUF score, 0.87, which puts it in group 3 of 6, group 1 being the genes least tolerant of losing a copy. Missense variants: 617 observed, 645.86 expected, observed/expected ratio (o/e) 0.96, 90% interval 0.89 to 1.02. Synonymous variants: 234 observed, 252.07 expected, observed/expected ratio (o/e) 0.93, 90% interval 0.83 to 1.03.